SPARC (secreted protein acidic and cysteine rich)
Description:
Appears to regulate cell growth through interactions with the extracellular matrix and cytokines. Binds calcium and copper, several types of collagen, albumin, thrombospondin, PDGF and cell membranes. There are two calcium binding sites; an acidic domain that binds 5 to 8 Ca(2+) with a low affinity and an EF-hand loop that binds a Ca(2+) ion with a high affinity.
Synonyms: BM-40; ON; ONT; OI17
Tractability: Small molecule: it has a binding pocket of medium quality. Antibody: UniProt places it where antibodies can reach, with high confidence; its Gene Ontology location is reachable by antibodies, with high confidence; UniProt predicts a signal peptide or a membrane-spanning region. PROTAC: ubiquitination databases record sites on it; its protein half-life has been measured.
Gene: Protein-coding gene on chromosome 5 (151,661,096 to 151,687,352, reverse strand). Ensembl gene ENSG00000113140.
Subcellular location: Secreted, extracellular space, extracellular matrix, basement membrane
Subcellular location (Human Protein Atlas): Vesicles; Predicted to be secreted
Pathways (Reactome):
Extracellular matrix organization: ECM proteoglycans
Hemostasis: Platelet degranulation
Signal Transduction: Nuclear signaling by ERBB4
Vesicle-mediated transport: Scavenging by Class H Receptors
Gene Ontology:
Molecular function: calcium ion binding; collagen binding; protein binding; extracellular matrix structural constituent; extracellular matrix binding
Biological process: negative regulation of angiogenesis; negative regulation of endothelial cell proliferation; positive regulation of endothelial cell migration; regulation of cell morphogenesis; regulation of synapse organization; semicircular canal morphogenesis
Cellular component: cell surface; cytoplasm; extracellular matrix; extracellular region; mitochondrion; nuclear matrix; plasma membrane; platelet alpha granule; platelet alpha granule membrane; endocytic vesicle lumen; platelet alpha granule lumen; basement membrane
Genetic constraint (gnomAD): Loss-of-function variants: 23 observed, 38.61 expected, observed/expected ratio (o/e) 0.6, 90% interval 0.43 to 0.84. The upper end of that interval is the gene's LOEUF score, 0.84, which puts it in group 3 of 6, group 1 being the genes least tolerant of losing a copy. Missense variants: 310 observed, 400.46 expected, observed/expected ratio (o/e) 0.77, 90% interval 0.7 to 0.85. Synonymous variants: 154 observed, 156.95 expected, observed/expected ratio (o/e) 0.98, 90% interval 0.86 to 1.12.
Homologues: Orthologues: chimpanzee SPARC (100% identical), macaque SPARC (99% identical), dog SPARC (97% identical), pig SPARC (96% identical), rabbit SPARC (95% identical), guinea pig SPARC (93% identical), mouse Sparc (92% identical), rat Sparc (92% identical), tropical clawed frog sparc (81% identical), zebrafish sparc (77% identical), Caenorhabditis elegans ost-1 (29% identical), Drosophila melanogaster SPARC (27% identical). Paralogues in human: SPARCL1 (52% identical).
Diseases named in the same sentence as SPARC in open-access papers:
SPARC is named in the same sentence as 344 diseases in open-access papers, as found by Europe PMC text mining. Sharing a sentence is not in itself a finding about the gene and the disease. The quoted sentences say what the papers report.
breast carcinoma (127 papers, 2003 to 2025). "The effects of SPARC on breast cancer are contested, as SPARC has been associated with both poor and favorable outcomes in disease progression." (PMID 40847127, 2025). "SPARC has been linked to stromal remodeling and poor prognosis in hepatocellular carcinoma and breast cancer, but its role in desmoplasia is particularly pronounced in PDAC." (PMID 41303383, 2025). "SPARC variants as biomarkers for breast cancer risk and prognosis have only been previously proposed in a case–control study." (PMID 38137452, 2023). "SPARC is an inhibitor of the migration and invasion of breast cancer, while resisting the platelet deficiency caused by it." (PMID 37577749, 2023). "SPARC-deficient microenvironment in breast cancer reduced primary tumor growth and lung metastasis, possibly due to the macrophages with SPARC-deficiency and unable to support stroma formation and collagen deposition." (PMID 36906534, 2023). "The inhibition of SPARC secretion by oleic acid ultimately favors T-cell activation as an underlying mechanism for the reduction of breast cancer aggressiveness." (PMID 37577749, 2023). "SPARC was highly expressed in breast cancer tissues and was associated with TNM staging and lymph node metastasis." (PMID 35211625, 2022). "For example, higher SPARC expression was associated with metastatic potential of melanomas, gliomas, and breast cancer." (PMID 35670884, 2022). "The role of SPARC in breast cancer remains in question, as it has been linked both to increased progression and decreased cancer cell proliferation." (PMID 33534863, 2021). "SPARC expression is widely associated with breast cancer, as approximately 75% of invasive breast cancers show strong SPARC expression, while in normal mammary tissue 92% of samples show undetectable or poorly detectable expression." (PMID 33534863, 2021). "Limited data have indicated that high SPARC expression is associated with a poor prognosis in patients with breast cancer." (PMID 28050738, 2017). "Immune cells, such as tumor-associated macrophages, also produce SPARC and enhance migration in murine animal models for breast cancer." (PMID 28969021, 2017). "In contrast, low SPARC expression in cancer tissue is associated with good prognosis in patients with lung cancer and breast cancer." (PMID 28718842, 2017). "α-SMA, TNC and SPARC, which represents the abundance of cancer-associated fibroblasts and extracellular matrix, have been linked to shorter survival in breast cancer in retrospective studies based on their gene or protein expression levels." (PMID 27487140, 2016). "In breast cancer, SPARC expression has largely been associated with a more aggressive phenotype and an unfavorable prognosis." (PMID 27544129, 2016). "A subgroup analysis according to breast cancer subtype showed that high SPARC expression was independently associated with low pCR rate, only in the HER2 subtype (OR: 0.15; 95% CI [0.02–0.77], p = 3.3E−02)." (PMID 23638089, 2013). "In the systemically untreated cohort (n = 948), we evaluated the association between SPARC/SPRAC7expression, breast cancer subtypes and clinicopathologic parameters." (PMID 23638089, 2013). "In our study, we chose the SPARC protein and the Murine leukemia virus (MuLV) gp70 protein as the tumor-associated antigen epitopes sources for cancer treatment in the mouse mammary cancer model." (PMID 41050655, 2025). "Our study shows that SPARC polymorphisms may have a prognostic and predictive value in breast cancer." (PMID 38137452, 2023). "In breast cancer, SPARC has been associated with worse prognosis and has pro‐tumor functions." (PMID 36346290, 2023).
breast carcinoma (continued). "Therefore, overexpression of SPARC by NVA-AA NPs supports the previous findings reporting the induction of apoptosis associated with high expression of SPARC in breast cancer." (PMID 37719007, 2023). "The future directions of our study include the two SPARC variants that could be good predictors of outcome in luminal breast cancer patients treated with neoadjuvant chemotherapy." (PMID 38137452, 2023). "Contradictory regulation of SPARC has been documented in the initiation and progression of cancer, although the majority of existing literature reveals that downregulation of SPARC is closely associated with the aggressive phenotype of breast cancer progression." (PMID 37719007, 2023). "However, there is also evidence that overexpression of SPARC in the stroma of breast cancer is associated with a decreased risk of bone metastasis, the main site of metastases for this type of tumor." (PMID 33946660, 2021). "A high expression level of SPARC expression is associated with high metastatic potential of glioma and melanoma, and is furthermore associated with the poor prognosis of prostate cancer and breast cancers." (PMID 28969021, 2017). "Notably, ET-1 and SPARC have diagnostic significance for patients, being highly expressed in dysplastic lesions adjacent to breast carcinoma and in pair-matched bone metastases." (PMID 27187355, 2016). "While some studies report a positive association between high SPARC and more aggressive tumors, several studies, including our own, support the view that it functions in part as a tumor suppressor in neuroblastomas, leukemias, colorectal, ovarian, pancreatic, lung, and breast cancers." (PMID 22069448, 2011). "Irisin, oncostatin and SPARC have, for example, been shown to suppress colon and breast cancer growth, and IL-6 and SPARC play roles in the prevention of cancers by exercise." (PMID 41300368, 2025). "In support of these findings, we found the same association between SPARC and Il-23 in the third BC model represented by SN25A (Sparc-KO) and SN25ASP (Sparc-high) breast cancer cells." (PMID 40890836, 2025). "Presence of SPARC in tumor stroma was reported to be responsible for recruitment of immunosuppressive myeloid cells in high-grade breast carcinomas." (PMID 40810390, 2025). "Since 1999, SPARC has been consistently reported to be overexpressed in various types of tumors, such as breast cancer, liver cancer, neuroblastoma, and glioma." (PMID 38323081, 2024). "GP60 is overexpressed in vascular endothelial cells, and SPARC is overexpressed in most tumor cells, such as breast cancer, glioma, melanoma, and liver cancer." (PMID 38323081, 2024). "While the SPARC level is relatively high in breast cancers, tumor morphology, density, and size, dose timing, number of doses, etc. are all important for drug retention as well." (PMID 39697343, 2024). "Nevertheless, the function of SPARC appears to vary among cancer types, and its role in breast cancer progression is controversial." (PMID 38137452, 2023). "SPARC, as a target protein that inhibits the cell cycle of breast cancer, is bound to increase the target of chemotherapy medicines." (PMID 37577749, 2023). "The upregulation of SPARC was observed after neoadjuvant chemotherapy is correlated with chemotherapy resistance in breast cancer patients." (PMID 37577749, 2023). "Previous studies reported that SPARC is overexpressed in TNBC compared with other breast cancer molecular subtypes." (PMID 36346290, 2023). "A high SPARC level correlated with breast cancer cell differentiation becomes a new therapeutic approach." (PMID 37577749, 2023). "SPARC has the ability to inhibit osteoclast activation in the microenvironment besides inhibiting breast cancer cell migration and invasion." (PMID 37577749, 2023). "In summary, SPARC expression is associated with worse survival in MESO, breast cancer, head and neck cancer, gastric cancer, and hepatocellular carcinoma." (PMID 37509139, 2023).
breast carcinoma (continued). "SPARC expression has been described in the stroma adjacent to the tumor epithelium, revealing its possible involvement in breast cancer invasion." (PMID 38137452, 2023). "Studies have reported that SPARC induction inhibits breast cancer cell proliferation, and down‐regulated expression of SPARC correlated with poor breast cancer prognosis." (PMID 36617746, 2023). "Currently, data regarding the value of SPARC expression as an outcome biomarker for the various molecular subtypes of breast cancer is limited and inconsistent." (PMID 38137452, 2023). "The high affinity between nal-paclitaxel’s functional structural protein, HSA, and SPARC is responsible for its excellent efficacy in the management of breast cancer." (PMID 37577749, 2023). "The emergence of a good target and prognostic indicator, SPARC, is going to open the door to a whole new world in the treatment of breast cancer." (PMID 37577749, 2023). "Methylation-mediated SPARC expression was shown to correlate with tumor progression and poor prognosis of breast cancer." (PMID 37509139, 2023). "After stage treatment, the expression of SPARC in the stromal cells will be used as a predictive pointer for breast cancer." (PMID 37577749, 2023). "SPARC expression has been extensively analyzed as a prognostic and treatment response biomarker in several cancer types, including breast cancer." (PMID 38137452, 2023). "As an EMT related gene, the prognostic value of SPARC has been reported in many tumors, like breast cancer and lung cancer." (PMID 38035023, 2023). "TAM-expressed stabilin-1 mediates clearance of tumor growth-inhibiting factor SPARC in a mouse model of breast cancer, and germinal knock-out of stabilin-1 results in the statistically significant reduction of primary tumor growth in this model." (PMID 36686729, 2022). "According to studies, SPARC is concentrated in the tumor stroma and overexpressed in breast cancer, lung cancer, melanoma cancer, and gastric tumors." (PMID 36415513, 2022). "According to Oncomine database, SPARC expression was upregulated in breast cancer than normal tissues." (PMID 35211625, 2022). "SPARC expression can be employed as a good indicator of prognosis of breast cancer patients, which will provide new methods and ideas of preventive treatment." (PMID 35211625, 2022). "It has been reported that the ectopic expression of integrin β3 induces the expression of SPARC in melanoma cells and that the β4 subunit regulates the expression of SPARC in breast cancer cells." (PMID 35682554, 2022). "A total of 20 articles that analyzed the relationship between SPARC expression and the clinicopathological characteristics of breast cancer were identified." (PMID 35211625, 2022). "The meta-analysis showed that SPARC expression was elevated in breast cancer tissue, compared with normal tissue, while SPARC expression in tumor stromal cells was higher than that of tumor cells." (PMID 35211625, 2022). "The purpose of our research is to clarify the clinicopathological and prognostic significance of SPARC expression in breast cancer." (PMID 35211625, 2022). "In our study, we performed a meta-analysis and bioinformatics analysis to confirm the relationship between SPARC mRNA expression and the clinicopathological factors of breast cancer." (PMID 35211625, 2022). "Pro-tumor: Supporting breast cancer progression through activation of PKCβ expression in TAMs resulted in SPARC uptake from TME by TAMs." (PMID 36686729, 2022). "Then, we analyzed, with a Real-Time PCR, the expression of two important CAF markers, such as FAP and SPARC (or osteonectin), in primary BCAFs and paraffin-embedded breast cancer tissues." (PMID 35743318, 2022). "For example, the higher levels of SPARC expression have been reported in breast cancer and glioblastomas, while the lower levels of SPARC expression have been found in ovarian, colorectal, and pancreatic cancers." (PMID 34912848, 2021).
breast carcinoma (continued). "Relative mRNA expression of SPARC was significantly higher in breast cancer MDA-MB-231 cells than in human breast epithelial cells (unpaired Student’s t test, P < 0.05)." (PMID 33763353, 2021). "In the present study, we also detected that SPARC was expressed at higher levels in breast cancer MDA-MB-231 cells than in normal breast epithelial MCF 10A cells." (PMID 33763353, 2021). "Here, we show that stromal expression of SPARC is significantly upregulated in breast cancer as compared to the normal breast in several different patient cohorts." (PMID 33534863, 2021). "In previous studies, the expression level of SPARC was found to be higher in human breast cancer tissue when compared with healthy breast tissue." (PMID 33763353, 2021). "To demonstrate that SPARC is cleaved by cath-D also in vivo, we first analyzed the level of FL SPARC and cleaved fragments in whole cytosols of mammary tumors from MMTV-PyMT Ctsd-/-knock-out mice." (PMID 33995652, 2021). "Cathepsin K from breast cancer cells activates osteoclasts, which promotes osteolytic bone metastasis, and cathepsin K from the bone marrow stromal cells promotes breast cancer bone metastasis by splicing and activating SPARC in breast cancer cells." (PMID 32674405, 2020). "SPARC has been found in a variety of human cancers (breast cancer, stomach cancer, ovarian cancer, etc.)and diabetes-related research." (PMID 32166110, 2020). "SPARC was found as a DEG in breast cancer bone metastasis, while wasn't in the list of the up- or down-regulated DEGs." (PMID 30918839, 2019). "In our study, we detected some published potential biomarker of breast cancer bone metastasis, or their function has been reported in breast cancer bone metastasis such as SPARC, IBSP, MMP9, MMP13." (PMID 30918839, 2019). "We specifically focus on how copper-binding proteins such as mediator of cell motility 1 (MEMO1), LOX, LOX-like proteins, and secreted protein acidic and rich in cysteine (SPARC) modulate breast cancer from molecular and clinical aspects." (PMID 28425924, 2017). "Ectopic expression of SPARC in high‐grade breast cancer cells leads to the acquisition of EMT features in vivo but not in vitro, highlighting the role of the microenvironment in this process." (PMID 28599100, 2017). "SPARC acts as a tumor inhibitor in breast cancer, colorectal cancer, ovarian cancer, prostatic cancer and pancreatic cancer, but in glioma SPARC serves as a tumor promoter via enhancing tumor invasion and metastasis." (PMID 29156791, 2017). "Stabilin-1 mediates phagocytosis of “unwanted-self” components, intracellular sorting, and endocytic clearance of extracellular ligands including SPARC that modulates breast cancer growth." (PMID 27105498, 2016). "According to three different clinical trials including melanoma, pancreatic, and neoadjuvant breast cancer, SPARC was considered as a predictive biomarker of response to nab-paclitaxel." (PMID 26731428, 2016). "We have proposed enhanced clearance of SPARC in wild type mice as a reason of increased tumor growth since tumor-inhibiting effect of extracellular SPARC in several types of cancer including breast cancer was widely demonstrated in vitro and in vivo." (PMID 27105498, 2016). "Several studies reported that SPARC inhibits primary growth of lung carcinoma, neuroblastoma and metastasis of breast cancer in animal tumor models." (PMID 27105498, 2016). "Several studies have suggested that SPARC expression is higher in TNBC than in other breast cancer subtypes, and correlates with poor prognosis, while other studies have shown nonsignificant or opposite results." (PMID 27421134, 2016). "SPARC expression was increased in 37% of TNBC tumor tissues (P = 0.038) compared with other breast cancer subtypes." (PMID 27421134, 2016). "In a large study of localized breast cancer, pre-treatment core biopsies were analyzed for SPARC expression by IHC." (PMID 27544129, 2016).